SNORA11 (small nucleolar RNA, H/ACA box 11)
Synonyms: U107; SNORA11A
Gene: Small nucleolar RNA gene on chromosome X (54,814,370 to 54,814,497, forward strand). Ensembl gene ENSG00000221716.
Gene Ontology:
Biological process: RNA processing
Cellular component: nucleolus
Homologues: Orthologues: macaque SNORA11 (91% identical). Paralogues in human: SNORA11D (85% identical), SNORA11E (85% identical), SNORA11F (85% identical), SNORA11C (84% identical), SNORA11B (84% identical), SNORA11G (73% identical).
Diseases named in the same sentence as SNORA11 in open-access papers:
SNORA11 is named in the same sentence as 4 diseases in open-access papers, as found by Europe PMC text mining. Sharing a sentence is not in itself a finding about the gene and the disease. The quoted sentences say what the papers report.
ameloblastoma (2 papers, 2017 to 2021). The most common odontogenic tumor, arising from the epithelial component of the embryonic tooth and usually affecting the molar-ramus region of the mandible or maxilla. "Further validation in an independent cohort points out the long non-coding (lncRNAs) and small nucleolar RNA (snoRNAs): LINC340, SNORD116-25, SNORA11, SNORA21, SNORA47 and SNORA65 as a distinct ncRNA signature of ameloblastoma." (PMID 27965463, 2017). "We have in this study reported significantly higher expression of a number of snoRNAs (SNORD116-25, SNORA11, SNORA21, SNORA47 and SNORA65) in ameloblastoma." (PMID 27965463, 2017). "Small nucleolar RNAs (snoRNAs) comprise a particular group of noncoding RNAs, which role in odontogenic tumors is still unknown, although the overexpression of SNORD116-25, SNORA11, SNORA21, SNORA47 was previously demonstrated in ameloblastomas." (PMID 33680332, 2021).
neoplasm (1 paper, 2017). A benign or malignant tissue growth resulting from uncontrolled cell proliferation. "SNORA11 has not until now been associated with other neoplasms, thus makes it unique in this perspective." (PMID 27965463, 2017). "It was found that the accumulated ncRNA levels (LINC340, LINC342, SNORD116-25, SNORA11, SNORA21, SNORA47, SNORA65; r = 0.5789, p-value = 0.0075) had a positive but moderate correlation with tumour size." (PMID 27965463, 2017).
SNORA11 also shares sentences with these, for which no sentence is quoted: hepatocellular carcinoma (1 paper); odontogenic tumors (1).